OCLN (occludin)
Diseases named in the same sentence as OCLN in open-access papers (continued):
Sharing a sentence is not in itself a finding about the gene and the disease.
subarachnoid hemorrhage (4 papers, 2015 to 2024). A serious neurological disorder characterized by intracranial hemorrhage into the subarachnoid space. "In particular, this type of polyphenol increased the levels of the anti-apoptotic protein Bcl-2 and tight junction proteins such us Zona Occludens 1 (ZO-1), claudin-5, and occludin, after subarachnoid hemorrhage." (PMID 39796474, 2024). "A previous study on other flavonoids proved its neuroprotective effect after SAH in rats through upregulating the expression of ZO-1 and occludin following subarachnoid hemorrhage (SAH), which was closely related to the integrity of the BBB." (PMID 29925377, 2018). "The expressions of ZO-1 and OCLN were significantly decreased after subarachnoid hemorrhage (SAH), and degrading ZO-1 and OCLN in endothelial tight junction can facilitate capillary leakage, which is responsible for the increase in BBB permeability after SAH." (PMID 26586924, 2015).
alcoholic liver diseases (3 papers, 2018 to 2022). A disorder caused by damage to the liver parenchyma due to alcohol consumption. "Moreover, inhibition of miR-122a increased intestinal occludin expression and protected mice from alcoholic liver disease." (PMID 30340459, 2018).
allergic reaction (3 papers, 2021 to 2025). "The allergic reaction did not affect the expression of Occludin in intestinal epithelial cells." (PMID 34684316, 2021).
astrocytoma (3 papers, 2015 to 2024). "Loss of expression of another transmembrane protein occludin in microvessels is also observed in astrocytomas and metastatic adenocarcinomas." (PMID 25866775, 2015). "To investigate localisation of occludin we initially used immunocytochemistry, which demonstrated diffuse cytoplasmic expression and punctate nuclear staining for occludin in both human primary astrocytes and the 1321N1 human astrocytoma cell line." (PMID 29738614, 2018).
bacteremia (3 papers, 2019 to 2025). "Furthermore, they saw the dephosphorylation of occludin and concluded that B. cenocepacia-induced dephosphorylation, and occludin dissociation could facilitate the migration of bacteria through the respiratory epithelium, leading to bacteremia." (PMID 36559113, 2022). "Intestinal occludin levels showed a significant correlation with circulating CRP at day 14 (p = 0.035, r = 0.45) as well as bacteremia (p = 0.06, r = 0.40)." (PMID 41266667, 2025).
campylobacteriosis (3 papers, 2019 to 2021). Infections with bacteria of the genus campylobacter. "Most importantly, with the macrophage activation and cytokine induction, which resembles the in vivo situation of the inflamed colon in campylobacteriosis, the colonic epithelial barrier damage promoted by C. concisus exacerbates via occludin and tricellulin disruption." (PMID 33669494, 2021). "Immunofluorescence studies demonstrated that infection of polarized intestinal Caco-2 cells with C. jejuni strain 81–176 resulted in a redistribution of occludin away from the tight junctions into the cytoplasm, an effect that was also observed in human biopsies during acute campylobacteriosis." (PMID 30805031, 2019).
cardiac arrest (3 papers, 2017 to 2026). Cessation of breathing and/or cardiac function. "Furthermore, NaHS exhibited neuroprotective properties in cardiac arrest models by reducing brain edema and BBB disruption through inhibition of matrix metalloproteinase-9 (MMP-9) expression and stabilization of occludin." (PMID 41465271, 2025).
cholangiocarcinoma (3 papers, 2015 to 2025). A carcinoma that arises from the intrahepatic biliary tree (intrahepatic cholangiocarcinoma) or from the junction, or adjacent to the junction, of the right and left hepatic ducts (hilar cholangiocarcinoma). "Loss of occludin protein was also observed in the gallbladder adenocarcinoma, poorly differentiated carcinoma from stomach and colon and cholangiocarcinoma as compared with the adjacent normal tissues and specific benign lesions." (PMID 31754355, 2019). "To investigate HCV entry factor expression in vivo we stained cholangiocarcinoma liver tissue from two donors with antibodies specific for CD81, SR-BI, claudin-1, occludin and epithelial marker CK19." (PMID 25701818, 2015).
coccidiosis (3 papers, 2019 to 2025). A parasitic infection caused by Coccidia. "Chickens with coccidiosis have lower occludin gene expression levels as a consequence of multiple factors, including inflammation." (PMID 31297194, 2019). "A downregulation in mRNA expression of FABP2 occurred in compromised gut barrier chickens (challenged with coccidiosis vaccine) along with decreased MUC2 and occludin expression, which may indicate an association between FABP2 and gut integrity in chickens." (PMID 34671361, 2021). "The depression of relative mRNA expression of JAM-2 and occludin observed during mixed Eimeria challenge in the current study is indicative of the impairment of the tight junction barrier due to sloughing of the intestinal epithelial cells and disruption of the mucus layer during coccidiosis." (PMID 41130050, 2025).
colonic adenocarcinoma (3 papers, 2022 to 2024). "TcdA and TcdB were also reported to induce remarkable disruption of occludin, ZO-1, and ZO-2 in T84 colonic adenocarcinoma cell line." (PMID 36303110, 2022). "TJP (occludin and zona occludens-1 (ZO-1)) levels and distribution profiles were assessed in HT-29 colon adenocarcinoma monolayers as an indication of gut barrier epithelial integrity." (PMID 36145318, 2022). "Furthermore, intervention with inosine (2 mM) in the human colonic adenocarcinoma cell line Caco-2 in vitro revealed that inosine could restore the downregulation transcription level of ZO-1 and Occludin induced by LPS." (PMID 39203495, 2024).
cyst (3 papers, 2019 to 2021). A sac-like closed membranous structure that may be empty or contain fluid or amorphous material. "In parallel, exposure to TNF-α to 3D Caco-2 cyst also attenuated the TJs integrity via dysregulating ZO-1 and OCCLUDIN on both mRNA and protein levels, and inducing deformed sinuous TJ belts at bicellular contacts." (PMID 30765731, 2019). "Similarly, TJal localization of occludin was shifted to an intracellular and a lateral membrane localization in the 2D transwell and the 3D cyst model, respectively." (PMID 33912578, 2021). "The ability of CP explants to generate cyst-like lumens after plating in Matrigel and the presence of tight junction markers ICAM-1, ZO1 and occludin indicates that CP explant cells provide intact barrier function." (PMID 32431599, 2020).
endometritis (3 papers, 2022 to 2024). An acute or chronic, usually bacterial infectious process affecting the endometrium. "Additionally, selenomethionine was reported to alleviate endometritis caused by Escherichia coli (E. coli) by upregulating ZO-1 and occludin and inhibiting NF-κB signaling." (PMID 39408650, 2024). "Therefore, we furthered evaluated the effect of C. butyricum on TJP expression in the E. coli-induced endometritis model, and determined the levels of ZO-1, claudin-3, and occludin using Western blotting." (PMID 36321897, 2022).
Heat Stroke (3 papers, 2017 to 2022). A condition caused by the failure of body to dissipate heat in an excessively hot environment or during PHYSICAL EXERTION in a hot environment. "Lastly, in the setting of fatal heat stroke, serum claudin-5, ZO-1, and occludin levels are unchanged." (PMID 30259344, 2018). "In patients suffering from a fatal heat stroke, increased expression values of OCLN were found, and authors suggested that it could be aimed at restoring junctional complexes and the barrier function as a compensatory mechanism." (PMID 35778683, 2022). "Heat stroke cases showed an increase in brain water content, which was found to be positively correlated with MMP9, OCLN, ZO1 and CLDN5 mRNA." (PMID 28490769, 2017). "When those four validated reference genes, SDHA, POLR2A, IPO8 and HMBS, were used for normalization, increased cerebral expressions of AQP4, CLDN5, OCLN, ZO1 and MMP9 were detected in heat stroke group." (PMID 28490769, 2017). "Relative mRNA quantification using Taqman real-time PCR assay demonstrated increased calibrated normalized relative quantity (CNRQ) values of MMP9, CLDN5, OCLN, ZO1 and AQP4 in heat stroke cases." (PMID 28490769, 2017). "The present study, for the first time, reports increased cerebral MMP9, CLDN5, OCLN, ZO1 and AQP4 in heat stroke and suggest a crucial role of reference gene selection when using postmortem human tissues." (PMID 28490769, 2017). "However, in the present study, increased CLDN5, OCLN and ZO1 mRNA expression was detected in the heat stroke group." (PMID 28490769, 2017).
hepatitis C virus infection (3 papers, 2014 to 2018). A viral infection caused by the hepatitis C virus. "In addition, hepatitis C recurrence after liver transplantation is associated with an increase of claudin-1 and occludin expression at the hepatocyte cell membrane." (PMID 26731658, 2016). "The TJ protein occludin functions in disparate processes, including wound healing and Hepatitis C Virus infection." (PMID 25422932, 2014).
Infertility (3 papers, 2013 to 2022). "Occludin (OCLN) is an epithelial tight junction protein and Ocln knockout (Ocln-KO) male mice are infertile; however, its physiological role and the mechanism underlying male infertility have not been known." (PMID 36518247, 2022). "Interference with the functional status of occludin protein in testicular SCs can result in infertility." (PMID 33194394, 2020). "Our data do not provide any evidence that the infertility of occludin knockout mice is due to dysfunction of the epididymal epithelium." (PMID 24236189, 2013).
interstitial cystitis (3 papers, 2021 to 2025). A rare chronic debilitating urogenital disease characterized by urinary frequency, urgency, and pelvic pain. "In patients with interstitial cystitis and painful bladder syndrome, the urothelium presents a similar decreased expression of occludin and ZO-1." (PMID 40566609, 2025). "Previous studies have already indicated alterations in the abundance and distribution of certain tight junction proteins, such as zonula-occludens 1, occludin, E-cadherin, and uroplakins in cats with FIC and human patients with interstitial cystitis." (PMID 36851436, 2023).
leukaemia (3 papers, 2006 to 2018). "Collectively, these results demonstrate that the loss of endothelial TJ proteins ZO-1, claudin-5 and occludin leaded by MMP-2 and -9 is a central event in the opening of the BBB in CNS leukemia." (PMID 21857898, 2011).
liver inflammation (3 papers, 2024 to 2025). "The tight junction proteins ZO-1 and Occludin play an important role in the regulation of intestinal permeability, and when this structure is disrupted, it leads to the translocation of LPS to the liver and blood system, causing liver inflammation and injury." (PMID 40444056, 2025).
malnutrition (3 papers, 2019 to 2022). Inadequate nutrition resulting from poor diet, malabsorption, or abnormal nutrient distribution. "Considering the relatively short intervention time and the improved immunity and levels of nutrition biomarkers such as IFN-γ, occludin, and prealbumin, C. butyricum could improve immunity and nutrition in older adults with malnutrition." (PMID 36079806, 2022). "We foresee some sort of dysfunction in the tight junction proteins, in a severe malnutrition, which could involve deformities in occludin and (ZO)-1 expression." (PMID 33799736, 2021).
mesothelioma (3 papers, 2017 to 2025). A usually malignant and aggressive neoplasm of the mesothelium which is often associated with exposure to asbestos. "In conclusion, our study demonstrates that occludin is overexpressed in metastatic HGSC compared to mesothelioma and may represent a novel diagnostic marker of this tumor, particularly in effusion specimens." (PMID 38141113, 2024). "Occludin protein expression was found in 587/602 (98%) HGSC vs. 40/87 (46%) mesotheliomas and was predominantly limited to < 5% of cells in the latter (p < 0.001)." (PMID 38141113, 2024). "In conclusion, occludin expression is higher in HGSC compared to mesothelioma, and this protein is overexpressed in HGSC effusions, possibly reflecting changes in adhesion related to anchorage-independent growth in this microenvironment." (PMID 38141113, 2024). "Occludin protein expression was found in 587/602 (98%) HGSC vs. 40/87 (46%) mesotheliomas and was predominantly limited to < 5% of cells in the latter, with significantly higher expression in HGSC (p < 0.001)." (PMID 38141113, 2024). "In the present study, occludin was significantly overexpressed in HGSC compared to mesothelioma specimens and was absent in reactive mesothelial cells, suggesting a potential diagnostic role." (PMID 38141113, 2024).
metabolic syndrome (3 papers, 2021 to 2025). A cluster of metabolic risk factors for CARDIOVASCULAR DISEASES and TYPE 2 DIABETES MELLITUS. "Men tend to accumulate visceral adiposity (VAT), which is associated with increased metabolic syndrome and cardiovascular risk, expressed as elevated serum lipopolysaccharide (LPS) levels and decreased expression of tight junction proteins (ZO-1, Occludin and Claudin-3), and widening of cell gaps." (PMID 40800131, 2025). "One study transplanted the faecal microbiota of patients with metabolic syndrome in mice, and assessed gut permeability, detecting lower mRNA levels of tight junction proteins (TJs), zonulin-1 (ZO-1) and occludin, and higher LPS plasma levels." (PMID 34933614, 2021). "Oral administration of Akkermansia can increase the number of goblet cells, restore the mucus thickness of the inner layer, and up-regulated the expression of tight-junction proteins including occludin, claudin, and ZO-1, in the gut of mice with metabolic syndrome." (PMID 34045965, 2021).
myopia (3 papers, 2014 to 2023). "The aim of this study was to detect the changes that occur in the expression of ZO-1 and occludin in the RPE-choroid complex of guinea pigs with lens-induced myopia (LIM), and to investigate the effect of RA on TJ-associated proteins in vivo." (PMID 24535401, 2014). "In the LIM and LIM plus PBS groups, the level of RA and the expression of ZO-1 and occludin in the RPE-choroid complex significantly increased within 14 days along with the development of myopia." (PMID 24535401, 2014). "Similarly, myopia progression remarkably decreased the mRNA level of Occludin and ZO-1 of the intestine." (PMID 38179454, 2023). "Thus, we consider that the expression of ZO-1 and occludin is increased in the RPE-choroid complex during the development of myopia." (PMID 24535401, 2014).
pancreatitis (3 papers, 2011 to 2024). Inflammation of the pancreas. "Several studies in humans have shown that patients with pancreatitis have intestinal barrier dysfunction accompanied by lower levels of occludin and ZO-1, both of which contribute to the stability of tight connections between cells as tight connection-related proteins." (PMID 32801992, 2020). "Similar results come from experimentally induced pancreatitis in rats where the mRNA levels of claudin 4, claudin 5 and occludin decreased due to pancreatitis induced lung injury but increased after administration of emodin, a chemical suggested to enhance epithelial barrier function." (PMID 21619599, 2011). "In pancreatitis, occludin, claudin-1 and ZO-1 are decreased, but no changes in claudin-4 have been reported; whereas E-cadherin and β-catenin are dissociated from the plasma membrane and condensed in the cytosol of acinar cells." (PMID 39030443, 2024).
psoriasis (3 papers, 2020 to 2022). An autoimmune condition characterized by red, well-delineated plaques with silvery scales that are usually on the extensor surfaces and scalp. "Clearly, the S. aureus infection associated-psoriasis group was characterized by a significant decrease of TJs expression, but the treatment with melatonin was able to significantly re-establish ZO-1 and occludin expression." (PMID 35453501, 2022). "In the psoriasis plaques, where the horny layer is missing or abnormal, occludin and ZO-1 are found in more layers than in normal epidermis." (PMID 32708987, 2020). "Inflammatory markers, that are typical in psoriasis, like TNF-α, IL1β, and mast cell degranulation, as well as occludin and ZO-1 tight junctions (TJs), were examined." (PMID 32708987, 2020).
pulmonary fibrosis (3 papers, 2020 to 2025). Chronic progressive interstitial lung disorder characterized by the replacement of the lung tissue by connective tissue, leading to progressive dyspnea, respiratory failure, or right heart failure. "ATG reduced the expressions of Vimentin and α-SMA (lung fibrosis markers) induced by PQ and restored the expressions of E-cadherin and Occludin (two epithelial markers) in vivo and in vitro." (PMID 33390951, 2020). "The authors speculated that the increased expression of OCLN may indicate a tightening of the epithelial barrier, which may be an adaptive mechanism in response to pulmonary fibrosis." (PMID 34823498, 2021).
Rotavirus infection (3 papers, 2020 to 2025). Infection with any of the rotaviruses. "Likewise, rotavirus infection disrupts Occludin-mediated TJ integrity in intestinal epithelial cells, increasing permeability and viral dissemination." (PMID 40142587, 2025). "Rotavirus infection significantly reduced ZO-1 and occludin expression." (PMID 32724066, 2020). "Similarly, during Rotavirus infection of IECs, a specific decrease in the occludin protein level at the TJ complex is reported as the result of the downregulation of occludin gene transcription with regulatory signals involving both Rp-cyclic AMP and PKA pathways." (PMID 33801524, 2021).
steatosis (3 papers, 2016 to 2025). Increased lipid within the cytoplasm of cells. "Enhance the expression of ZO-1, Claudin-1 and Occludin, decrease the expression of LPS, TNF-α, IL-6 and IL-1β, enhance intestinal barrier, and reduce inflammatory response, hepatocyte steatosis and collagen fiber deposition." (PMID 39234554, 2024).
ulcers (3 papers, 2025). "Furthermore, CRPs upregulate TJs proteins expression (occludin, ZO-1, Claudin-5) to restore both the structural and functional integrity of the gastric mucosal barrier, consequently preventing ulcer progression." (PMID 40647169, 2025).
vitamin D deficiency (3 papers, 2017 to 2023). A nutritional condition produced by a deficiency of VITAMIN D in the diet, insufficient production of vitamin D in the skin, inadequate absorption of vitamin D from the diet, or abnormal conversion of vitamin D to its bioactive metabolites. "We did not observe an effect of vitamin D deficiency or subsequent supplementation with vitamin D3 on occludin expression by lung epithelial cells." (PMID 28774952, 2017). "In clinical studies, a vitamin D deficiency caused the decreased expression of VDR, occludin, E-cadherin, and zonula occludens-1 in patients with UC, and the reduced expression of claudin 1, occludin, zonula occludens, and junctional adhesion molecules in patients with CD." (PMID 38258040, 2023).